IL1B (interleukin 1 beta)
Diseases named in the same sentence as IL1B in open-access papers (continued):
Sharing a sentence is not in itself a finding about the gene and the disease.
liver fibrosis (continued). "Considering the pathogenic importance of NLRP3 inflammasome-induced pyroptosis in liver fibrosis, we measured the levels of key markers for pyroptosis, including NLRP3, pro-caspase-1, cleaved Caspase-1, cleaved GSDMD-N, IL-1β, and IL-18." (PMID 34839365, 2021). "Further in vivo experiments validated the significant mitigatory effects of SNS on inflammatory infiltration and pro-inflammatory cytokine contents (IFNγ, IL-1β and TGF-β1) in liver tissues of mice with liver fibrosis." (PMID 34276360, 2021). "Compared to the positive control group, treatment of RBO at both dosage levels (0.2 and 0.4 mL/rat) for two weeks after development of liver fibrosis made a considerable reduction in liver content of TNF-α, IL-1β, and NF-κβ." (PMID 34965258, 2021). "In cattle, liver fibrosis has been proposed as a downstream effect of upregulated TNF and IL1B, which would activate the genes that were also upregulated in the bovine study, i.e., IL6, PLAU, SERPINE1, TNFRSF1A, SOCS1, and CTSB." (PMID 34616397, 2021). "Next, through the feedback mechanism, the secretion of a large number of proinflammatory cytokines, such as IL-1β and TNF-α, is increased, which further promotes liver steatosis, inflammation, and liver fibrosis." (PMID 34095305, 2021). "Other studies evaluating the role of caspase-1 and IL-1β knock-out animals have demonstrated the animals to be protected from NASH and liver fibrosis induced by high-fat diets." (PMID 32331389, 2020). "Among these cytokines, IL-1β and TGF-β are closely related to liver fibrosis due to their capacity to activate HSCs." (PMID 32733951, 2020). "Currently, some researchers believe that a combination of TFAs and fructose induces oxidative stress and increases TNFα, IL-6, IL-1β and collagen-Iα expression levels, which partly explained the roles of TFA and fructose in liver fibrosis progression." (PMID 32508961, 2020). "Afterwards, the cytoplasmic contents, including IL-1β, IL-18, TGF-β, and connective tissue growth factor (CTGF), will be released into the extracellular environment, facilitating the development of liver fibrosis." (PMID 32733951, 2020). "We analyzed liver IL-1β and IL-1Ra mRNA expression levels using RT-PCR, in both BDL- and CCl-4-induced liver fibrosis models." (PMID 30875826, 2019). "Overall, these results showed that IL-1β and IL-1Ra are upregulated during BDL-or CCl-4-induced liver fibrosis." (PMID 30875826, 2019). "Inflammatory macrophages, which promote inflammation and liver fibrosis, are activated by Toll-like receptors (TLR), with release of inflammatory (TNF, IL-1β) and pro-fibrogenic mediators (TGF-β and Gal-3) as well as chemokines (MCP-1, CCL5)." (PMID 31015492, 2019). "Activation of HSCs during liver fibrosis mainly depends on KC secretion of TGF-β1, the most powerful modulator, and, to a lesser extent, IL-1β." (PMID 30186272, 2018). "In this study, we found that BBG significantly ameliorated liver fibrosis and down-regulated fibrosis-related pro-inflammatory cytokines IL-6, TNF-α, IL-1β, and PDGF." (PMID 25933224, 2015). "Taken together, BBG reduces hepatic pro-inflammatory cytokines IL-6, TNF-α, PDGF, and IL-1β expressions, down-regulates TGF-β signaling pathway, and ameliorates liver fibrosis." (PMID 25933224, 2015). "D-Glucuronolactone, naturally abundant in animal livers, demonstrates hepatoprotective effects by enhancing the activity of antioxidant enzymes (SOD, GPx and GSH) and decreasing the production of inflammatory cytokines (IL-1β, IL-6 and TNF-α) in thioacetamide-induced liver fibrosis models." (PMID 41195363, 2025). "A recent study found that, in a mouse model of CCl4-induced liver fibrosis, the Citrus aurantium extract astragalin inhibited the expression of TNF-α, IL-18, and IL-1β mRNAs in the livers of fibrotic mice through the NF-κB/NLRP3 inflammasome pathway, significantly ameliorating liver fibrosis." (PMID 39995661, 2025).
liver fibrosis (continued). "Similarly, the 15 mg/kg dose exhibited greater efficacy, reducing IL-6 and IL-1β levels by 54.62% and 47.06%, respectively, and enhancing IL-10 levels by 227.27% as compared to TAA-induced liver fibrosis group." (PMID 41365955, 2025). "p-hydroxycinnamic acid, a natural phenolic compound, was reported to suppress the TLR4/NF-κB signaling pathway, reduce IL-1β precursor expression, and attenuate NLRP3 inflammasome activation in a mouse model of high-fat, high-sucrose diet-induced liver fibrosis, thereby inhibiting HSCs activation." (PMID 40661312, 2025). "Our study showed that E-T/LNPs downregulated the expression of IL-1β and TGF-β, suggesting that the mechanism of E-T/LNPs may be to ameliorate hepatic fibrosis by regulating the expression of inflammatory and fibrogenic factors." (PMID 39519763, 2024). "In liver fibrosis models, such as those induced by dimethylnitrosamine (DMN), resveratrol reduces inflammatory cell infiltration and fibrosis, lowering MDA levels, increasing GPx and SOD levels, and inhibiting inflammatory mediators like NO, TNF-α, and IL-1β." (PMID 39273295, 2024). "Additionally, IL-1β induces the expression of fibrogenic factors, such as TGF-β, CTGF and PDGF, which further promote liver fibrosis." (PMID 38595921, 2024). "IL-1β and TGF-β play important roles in the development of hepatic fibrosis." (PMID 39519763, 2024). "Lack of Surf4 also significantly reduced the expression of liver fibrosis markers (Col1a, Acta2/α-Sma) and inflammation markers (Il-1β and Tnf-α) at mRNA and protein levels in male and female Surf4LKO mice." (PMID 39105051, 2024). "Generally, IL‐1β is known to be part of the NOD‐like receptor family pyrin domain containing three inflammasome, which is involved in the upregulation of inflammation and liver fibrosis markers." (PMID 38798075, 2024). "The results showed that BMP could inhibit the proliferation of HSCs-T6 induced by LPS and decrease the levels of TGF-β1, IL-1β and TNF-α, indicating that BMP has a good effect on anti-hepatic fibrosis and relieving related inflammation." (PMID 38576476, 2024). "Furthermore, low expression IL-1β levels and high NFS values were independent predictors of hepatic fibrosis in MAFLD patients using multiple stepwise linear regression analysis." (PMID 39179677, 2024). "Numerous studies have demonstrated that IL-1β expedites ALD progression by amplifying the production of pro-inflammatory cytokines, upregulating fatty acid synthesis, inducing liver steatosis, and promoting liver fibrosis." (PMID 38507458, 2024). "IL-1β can also promote the activation and proliferation of HSCs through the p38 MAPK and JNK signaling pathways as well as the synthesis of Collagen-I to enhance the progression of liver fibrosis." (PMID 39407108, 2024). "Taken together, these findings suggested that SWT might ameliorate hepatic fibrosis by potentially inhibiting the adhesive process mediated by COL8A1, the angiogenesis process mediated by IL-1β and the LCEC defenestration mediated by OLR1." (PMID 39741334, 2024). "IL-6, TNF, and IL-1-β may act synergistically with TGF-β, and the genetic deletion of these cytokines may reduce the development of liver fibrosis." (PMID 39063116, 2024). "A significant increase in the mean relative gene expression levels of both IL-1β and NLRP3 found in patients with early fibrosis (F0-F1-2); 31.97 ± 11.8 and 6.76 ± 2.18, respectively; compared with patients with advanced hepatic fibrosis stages (F2-F3); 2.62 ± 3.71 and 4.27 ± 2.99 (p < 0.001 each)." (PMID 39179677, 2024). "TRIM38 directly binds to TAB2, and recognizes the K63 of RIP1 in the TNF-α signaling pathway through TAB2 to connect the ubiquitin chain or TRAF6 in the IL-1β signaling pathway, thereby inhibiting the key pathway TAK1-MAPK cascade in the process of liver fibrosis." (PMID 37867509, 2023).
liver fibrosis (continued). "Activated HSCs are identified by the overexpression of α-SMA and extreme expression of extra cellular matrix proteins (vimentin, β-catenin, and snail) through inflammatory cytokines such as TNF-α, IL-1β, and IL6, which increase the development of liver fibrosis." (PMID 37090196, 2023). "Besides the virus itself, the release of pro-inflammatory cytokines, especially IL-1β, plays a crucial role in promoting HBV-induced liver fibrosis." (PMID 37122751, 2023). "In vitro studies show that IL-1β and IL-18 regulate HSC activation and promote hepatic fibrosis." (PMID 36834849, 2023). "Accumulating evidence indicates that besides the virus itself, the release of pro-inflammatory cytokines, especially IL-1β, may play a more crucial role in promoting HBV-induced liver fibrosis." (PMID 37122751, 2023). "In vivo experiments have shown that it could reduce liver fat content, alleviate the expression of liver fibrosis indicators and autophagy, and inhibit the expression of NLRP3, ASC, caspase-1, and IL-1β." (PMID 36016562, 2022). "Consistently, the mRNA levels of inflammatory mediators TNF-α and IL-1β, as well as IL-6, ICAM, CCL2, CXCL2, and TGF-β, which were indicated as progressive inflammatory response and liver fibrosis, were significantly elevated in the liver of MFG-E8 knockout mice compared with the MCD-WT group." (PMID 35769208, 2022). "Gardenoside can ameliorate lipid deposition and liver fibrosis, and has been shown to decrease the expression levels of dipeptidyl peptidase-4 (DPP4), CCCTC-binding factor (CTCF), NLRP3, ASC, caspase-1 p20, GSDMD-N, and IL-1β in vitro and in vivo NAFLD models." (PMID 36016562, 2022). "PA could also significantly up-regulate SOD and GSH-px levels (p<0.01), down-regulate IL-1β, IL-18, caspase-1, NLRP3, and TNF-α protein or gene expression in PBC mice (p<0.01) and inhibit liver fibrosis levels (p<0.01)." (PMID 35195182, 2022). "The global cytokine surveys of HSC-CM have demonstrated that TNF-α, agrin, PDGF, activin A, GM-CSF, IFN-γ, IL-1β, IL-4, IL-6, IL-10, IL-13, and TIMP-1, which subsequently induce acute inflammation and liver fibrosis, were elevated in aHSC-CM relative to the qHSC-CM." (PMID 36142683, 2022). "In this study, we found that TRPM8 inhibition could reduce the F4/80 positive cell population and inhibit the transcript levels of IL-6, IL-1β, TNFα, and MCP-1 in murine models of liver fibrosis." (PMID 35525986, 2022). "Activated KC generates various types of mediators of liver fibrosis progression (e.g., TGF-β, PDGF, IL-1β, MMPs, CCL2, cysteine-3, etc.)and also accelerates the progression of liver fibrosis by activating HSC to produce large amounts of collagen, allowing ECM to settle and aggregate." (PMID 35529927, 2022). "Furthermore, it was observed that the levels of Acta2, Col1a1, Col3a1, Tnfa, Il6, and Il1β genes were significantly increased upon STAT3 overexpression, again suggesting that STAT3 mitigated liver fibrosis." (PMID 36588728, 2022). "Based on the role of S100A8-elicited NLRP3 pyroptosis in liver fibrosis, we chose a well-defined cohort of liver fibrosis patients to assess the clinical importance of circulating S100A8, GSDMD, IL-1β, and IL-18 for predicting the occurrence and progression of disease." (PMID 36429008, 2022). "Moreover, administration of IL-22 inhibits HSC activation, reduces the production of pro-inflammatory factors (IL-1β, IL-6, and TNF-α), and ameliorates liver fibrosis in CCl4-induced liver fibrosis." (PMID 33869241, 2021). "SolB reverses hepatic fibrosis by inhibiting hepatocyte injury, and WeD could block the production of TNF-α and IL-1β in macrophages and the activation of TGF-β1/Smad signaling pathway in activated HSCs." (PMID 34149411, 2021). "Moreover, expression of proinflammatory cytokines (IL-1β and TNF-α) and liver fibrosis markers (TGF-β and SM-α) which are driving forces of many liver disorders was also determined." (PMID 34707781, 2021).
liver fibrosis (continued). "In addition, liposomal (SPB) hydroalcoholic extract treatment decreased the liver expression of inflammatory cytokines (IL-1β, TNF-α) and liver fibrosis markers (TGF-β and SM-α)." (PMID 34707781, 2021). "Another study testing an inhibitor targeting the IL-1β pathway in liver fibrosis was performed on mice with non-alcoholic steatohepatitis." (PMID 34909658, 2021). "The conversion of Ly6Chi to Ly6Clo macrophages significantly downregulated the expression levels of Ly6Chi macrophage-derived PDGF, TNF-α, and IL-1β in the fibrotic liver, which was accompanied with the reduced expression of HSC-derived α-SMA and Col1α1 and the reduction of liver fibrosis." (PMID 34518510, 2021). "Our data showed that PHI had a good anti-inflammatory effect in mice with CCl4-induced liver fibrosis, which represented as the reduction of serum LPS, MIP-1 and TNF-α levels as well as the decreased expressions of three inflammatory factors (IL-1β, IL-6, and TNF-α) in liver tissue." (PMID 34621179, 2021). "Finally, in order to explore the role of WEPE in the inflammatory response of liver fibrosis, we evaluated the levels of TNF-α, IL-1β, and IL-6 in the rat serum." (PMID 34712342, 2021). "Also, the inhibition of IL-1β in hypercholesterolemic mice inhibited the progression of simple steatosis to NASH and liver fibrosis." (PMID 34439470, 2021). "Expression of IL-6, IL-1β, and TNF-α was also decreased in the acute hepatic fibrosis model." (PMID 33262757, 2020). "Our results showed that EP could inhibit HSC activation as EP significantly downregulated the HMGB1 level at 4 and 6 weeks of liver fibrosis induced by BDL, while IL-1β and TNF-α levels decreased substantially." (PMID 31933629, 2019). "However, emodin administration was able to decrease the hepatic expression of IL-1β, TNF-α, GRN, and TGF-β1 in the liver fibrosis model, which also explains why emodin can alleviate liver inflammation and fibrosis." (PMID 29743924, 2018). "Consistently, our in vivo studies showed that inhibition of IL-1β level with caspase-1 inhibitor dramatically reduced MPO activity in the liver and ameliorated liver fibrosis in BDL mouse model, suggesting an important role of IL-1β in triggering tissue inflammation and fibrosis during cholestasis." (PMID 27924062, 2016). "BBG also ameliorated liver fibrosis and down-regulated hepatic interleukin-6 (IL-6), tumor necrosis factor-alpha (TNF-α), PDGF, IL-1β, transforming growth factor-beta (TGF-β), p-extracellular-signal-regulated kinases (ERK), and alpha-smooth muscle actin (α-SMA) expressions in CBDL rats." (PMID 25933224, 2015). "The increased hepatic levels of Ppargc1a in TKO-HFD mice may counteract the effect of IL-1β through increased anti-inflammatory signaling, suggesting that TKO mice may also be protected against hepatic fibrosis." (PMID 26168159, 2015). "Ursolic acid inhibits KC pyroptosis in liver fibrosis in vitro and in vivo by suppressing the protein expression of pyroptosis-related indicators (NLRP3, pro-caspase-1, cleaved caspase-1, GSDMD, GSDMD-N, and IL-1β) in the NOX2/NLRP3 inflammasome signaling pathway." (PMID 40667485, 2025). "In accord, our work in experimental steatohepatitis and hepatic fibrosis reveals an up-regulation of the TGFβ signaling pathway and proinflammatory cytokine expression (i.e. IL-1β, IL-6, and TNFα) in mice lacking CNP; moreover, many of these pathogenic processes can be reversed by CNP treatment." (PMID 39816244, 2025). "Furthermore, pre- infection with T. spiralis markedly reduced S. mansoni- induced hepatic fibrosis, as evidenced by decreased collagen deposition, low expression of α-SMA, and significantly reduced levels of IL-17, IL-1B, IL-6, TGF-B, IL-23, and TNF-α compared to mice infected with S. mansoni only." (PMID 39439825, 2024).
liver fibrosis (continued). "Importantly, VSC-CDs demonstrated a mitigating effect on CCl4-induced liver fibrosis, as evidenced by the reduction in inflammatory cytokines (TNF-α, IL-6, IL-1β), elevation in antioxidant levels (SOD and GSH), and a decrease in lipid metabolites (MDA) to counteract oxidative stress damage." (PMID 38116381, 2023). "Moreover, Anakinra treatment alleviated liver injury and inflammation without affecting fibrosis in a mouse model of CCl4-induced liver fibrosis, as shown by a decrease in caspase-1 and IL-1β with unchanged CTGF and TIMP expression." (PMID 35707547, 2022). "Thus, IL-1β-activated mTORC2 signaling in γδ T cells upregulates CXCR3 expression, which is critical for IFN-γ+ γδ T cells migration into the liver and amelioration of liver fibrosis." (PMID 35361750, 2022). "On this note, elevated oxidative stress has been shown to promote liver fibrosis by stimulating the generation of collagen from the activated hepatic stellate cells and release of other profibrotic (TGF-β, α-SMA), chemotaxis (MCP-1) and proinflammatory (IL-1β, TNF-α) mediators." (PMID 34427662, 2021). "In addition, the effects of CVC on liver fibrosis are related to the reduction of inflammation-related biomarkers, such as IL-6, IL-1β, etc., which indicates that CVC is a great potential anti-liver fibrosis candidate drug because inflammation is one of the important factors causing liver fibrosis." (PMID 34621747, 2021). "Besides, IL-1β does not figure predominantly in the pathogenesis of chronic liver diseases including liver fibrosis." (PMID 34712238, 2021). "In this study, we showed that lnc-Lfar1 silencing alleviated liver injury-induced upregulation of LY6C, IL-1β, IL-6, TNF-α, MCP-1, CCL5 and CXCL10 in vivo and in vitro, suggesting that lnc-Lfar1 knockdown might be beneficial for preventing liver fibrosis by targeting these chemokines." (PMID 32071306, 2020). "Decreasing the levels of IL-1β, IL-6, and TNF-α could alleviate CHI and hepatic fibrosis." (PMID 33144872, 2020). "Even though HCC may develop in healthy liver parenchyma, in most cases it develops in chronic inflammatory liver parenchyma in pathology secondary to the induction of trained immunity depending on IL-1β production (NAFLFD, ALD, Viral chronic hepatitis, hepatic fibrosis)." (PMID 31507607, 2019). "Also, due to the fact that they are able to process extracellular matrix and activate pro-fibrotic cytokines such as IL-1β and IL-33 (Interleukin-33), PR3 and NE might play an important role in the mechanisms of liver fibrosis." (PMID 31046673, 2019). "Interestingly, MCD-induced NASH in NLRP3−/− mice showed that serum alanine transaminase (ALT), aspartate transaminase (AST), IL-1β, and IL-18 levels were lower than those in non-knockout mice and significantly reduced hepatocyte inflammation, hepatomegaly, and liver fibrosis." (PMID 36016562, 2022). "Therefore, it is concluded that the activation of NLRP3 inflammatory bodies mediated by P2X7R may be involved in the production of IL-1β in hepatic stellate cells, and blocking the axis of P2X7R-NLRP3 inflammatory bodies may be a potential target for the treatment of hepatic fibrosis." (PMID 35002763, 2021). "Therefore, decreasing expression level of IL-1β and NLRP3 and increasing values of NFS can be used as non-invasive methods to assess advanced hepatic fibrosis." (PMID 39179677, 2024). "Previously, it was reported that upstream blockade of IL-1β maturation by NLRP3 inflammasome and caspase-1 inhibition reduced hepatic fibrosis, proving that lacking IL-1β in NASH may ameliorate pro-fibrotic events." (PMID 36611037, 2023). "Furthermore, the machinery of the inflammasome pathway (which regulates the maturation and liberation of IL-1β) is known to be expressed by HSCs, and mice lacking inflammasome components suffer from lower levels of CCl4- and TAA-induced liver fibrosis." (PMID 27046197, 2016).